TNF (tumor necrosis factor)
Diseases named in the same sentence as TNF in open-access papers (continued):
Sharing a sentence is not in itself a finding about the gene and the disease.
cancer (continued). "A previous study suggests that TNF-α is also important in determining cell invasion of cancer cells." (PMID 33730072, 2021). "The induction of EMT by TNF-α synergizing with TGF-β or other inflammatory factors has been described in human cancer cell lines in vitro." (PMID 34576042, 2021). "Pathway analysis showed that the dysregulated genes are involved in multiple cancer-related pathways, such as TNF signaling, NF-κB signaling, and c-AMP signaling, etc." (PMID 34316028, 2021). "Anakinra is mainly used as a second-line treatment in patients previously treated with a failing anti-TNF-α therapy or experiencing cancer or infectious disease such as Mycobacterium tuberculosis infections." (PMID 34201546, 2021). "The upregulation of cancer-promoting inflammatory cytokines (host and tumor-secreted), such as NF-κB, COX-2, IL-1, IL-6, TNF-α, and IFN-γ, is strongly associated with STAT3 and AKT signaling activation in oral squamous cell carcinoma in vitro." (PMID 34950252, 2021). "The methanolic extract of CP wood demonstrated potent free radical scavenging activity, and the isolated cochinchinone B triggers several different cancer cells line to die by TNF-α-dependent apoptosis, the antagonizing effect of the NF-κB." (PMID 34299510, 2021). "This work describes TNFα participation as a source of treatment resistance and its implication in side effects to immunotherapy, as well as its participation in different cancer types, where TNFα can be a suitable target to improve therapy outcome." (PMID 33540543, 2021). "TNFα is one of the major pro-inflammatory cytokines of the immune system and has been found in several human cancers, such as breast, gastric, pancreatic, ovarian, endometrial, prostate, bladder, colorectal, oral, and liver." (PMID 33540543, 2021). "NF-κB, STAT3, and the major pro-inflammatory cytokines of the interleukin family, i.e., IL-1β, IL-6, IL-23, and TNF-α (tumor necrosis factor-alpha), are considered the key endogenous cancer-related inflammatory factors." (PMID 33546238, 2021). "SIR is characterized by an increase in concentration of inflammatory factors, such as CRP, TNF-α, IL-1, IL-6, INF-γ, and PIF (previously known as “cancer cachectic factor” or cachexia-associated protein)." (PMID 33557173, 2021). "The m6A-C2 phenotype is more characteristic of cancer and immune surveillance, and it is associated with EMT, TGF-β, and TNF-α pathway activation and is an immune-excluded phenotype." (PMID 34993195, 2021). "RIP1 was essential for cellular response to TNF-α and smac mimetic, but dispensable for the response to anti-cancer drugs." (PMID 33800107, 2021). "For patients aged 40–64 years, the unique cancer-related BP terms were mainly related to cellular response to tumor necrosis factor, protein kinase A signaling, peptidyl-tyrosine phosphorylation, and regulation of phosphatidylinositol 3-kinase activity." (PMID 33968126, 2021). "KEGG analysis showed that the upregulated genes in Epi-SCs and SKPs were enriched in signals of PI3K/Akt, cancer, TNF signaling, and extracellular matrix (ECM) interaction, among them PI3K/Akt signaling pathway ranked top in Epi-SCs." (PMID 32245516, 2020). "Another study showed that TAMs can promote ROS generation within cancer cells through tumor necrosis factor alpha (TNFα) secretion." (PMID 33187272, 2020). "TNF levels are raised in multiple cancer types, are reduced by chemotherapy and the reduction is associated with patient outcomes." (PMID 32805626, 2020). "In the cancer cachexia condition, inflammatory factors, such as TNF-α, IL-1, and IL-6, can activate p38 MAPK signaling, thereby inhibiting PGC-1α transcription and reducing energy production." (PMID 33102208, 2020). "Chronic inflammation including cancer increases the monocyte count by the secretion of various cytokines such as TNF-α, IL-1, and IL-6." (PMID 32552873, 2020).
cancer (continued). "AIM suppressed the TNF-α effects on the NF-κB-regulated proteins involved in cancer cell proliferation (COX-2, C-myc), invasion, and angiogenesis (MMP-2, MMP9, ICAM-1, and VEGF)." (PMID 32455624, 2020). "Literature suggests that TNF-α can induce both apoptosis and inhibit apoptosis through NF-κB activation in cancer cells." (PMID 32784919, 2020). "Experimental studies on the effect of hepatic ischemia-reperfusion on the outgrowth of cancer cells revealed hepatocyte dysfunction and increased inflammatory cytokines such as TNF-α as well as matrix metalloproteinases." (PMID 33383844, 2020). "As many cancers have evolved resistance to cell death via apoptosis, the ability of SMs to regulate the TNF cell death pathways through promoting both apoptosis and necroptosis provides a promosing novel therapeutic avenue towards resistant malignancies." (PMID 32053868, 2020). "More recently, TNFα has been shown to promote the expression of PD-L1 in cancer cells, leading to immunosuppression." (PMID 32391269, 2020). "For example, tumor necrosis factor-alpha (TNF-α) and interleukin 6 (IL-6), the main cytokines released during chronic inflammation, are known to stimulate proliferation of cancer cells, their survival and their dissemination." (PMID 33013813, 2020). "GSEA on Hallmarks of Cancer identified apoptosis and TNFα through NFκB as being significantly altered." (PMID 33163396, 2020). "Cancer cells are embedded in a very complex microenvironment that consists of a variety of such environmental stressors, including TNF‐α." (PMID 32239615, 2020). "It was found that the predictability of cancer onset by measuring salivary TNF levels in 42 people is possible." (PMID 32019214, 2020). "The expression level of miR-381-3p inversely correlates with the sensitivity of cancer cells to TNF-induced apoptosis." (PMID 32411707, 2020). "And indeed, the mRNA levels of JUN and the membrane-bound TNF of these human cancer cells were also upregulated in response to treatment with MTAs." (PMID 31645676, 2020). "Adipocytes communicate with surrounding cells by secreting pro-inflammatory cytokines (IL-6, IL-1β, and TNF-α) and MMPs, which modulate cancer metabolism." (PMID 33322132, 2020). "Pseudoalteromonas cPrG was shown induce apoptosis in several cancers including acute human T-cell leukemia, acute promyelocytic leukemia, human and rat hepatocellular cancer, human breast cancer, and TNF-stimulated human cervix carcinoma." (PMID 33364537, 2020). "In particular the cytokine tumor necrosis factor α (TNFα), previously called cachectin, has been demonstrated to be a major player in cancer related cachexia as it is able to induce muscle wasting through NFkB pathway." (PMID 32373612, 2020). "TRAIL is a member of tumor necrosis factor (TNF) family which, when bound to DR5, can cause apoptosis in a variety of cancer cell types, while sparing normal cells." (PMID 33374919, 2020). "The main enriched pathways are cancer pathway, chemical carcinogenesis, estrogen signaling pathway, TNF signaling pathway, and leukocyte transendothelial migration." (PMID 32849897, 2020). "Tumor necrosis factor (TNF)-related apoptosis-inducing ligand (TRAIL) plays an important role in cancer therapy by inducing selective apoptosis of cancer cells while having little effect on the normal cells." (PMID 32987767, 2020). "Previous studies in diverse cancer cell lines have shown that EBI3 expression can be induced by TNFα stimulation via NFκB promoter activity." (PMID 31955243, 2020). "Regulated genes in response to cartilage fragments were enriched in pathways including proteoglycan in cancer, gluconeogenesis, TNF signaling pathway, Toll-like receptor signaling pathway, and phagosome." (PMID 32371954, 2020). "ADAM proteins can cleave various substrates, including TNF-α, an epidermal growth factor involved in inflammation and cancer." (PMID 32028607, 2020).
cancer (continued). "Leptin gene expression is up-regulated by pro-inflammatory cytokines, such as TNFα and IL-1, which are also involved in the pathophysiology of cancer cachexia." (PMID 32660156, 2020). "Previous reports have shown that the stimulation of TNF-α results in the upregulation of caspases 3/7, which leads to apoptosis in various cancer cells." (PMID 32397330, 2020). "Considering the pleiotropic and conflicting effects of TNF-α, various efforts have been made to exploit this cytokine as a therapeutic target in cancer." (PMID 32883235, 2020). "Collectively, our findings strongly support a previous study which found that TNFα increases cytotoxicity of anticancer drugs such as DOX to cancer cells, because TNFα is a strong activator of NF-κB signal." (PMID 32225068, 2020). "TNF-α can also exhibit prometastatic activity on its own through increased production of chemokines inducing angiogenesis and enhancing cancer cell motility, which has been thoroughly reviewed in previous publications." (PMID 33322371, 2020). "AIM suppressed TNF-α effects on the NF-κB-regulated proteins involved in cancer cell proliferation (COX-2, and C-myc), invasion, and angiogenesis (MMP-2 and MMP9, ICAM-1 and VEGF)." (PMID 32455624, 2020). "Since its discovery as a regulator of tumor necrosis factor mRNA stability more than 20 years ago, TTP has become notable for its mediation of multiple cancers and immunity-associated transcripts." (PMID 32784606, 2020). "Further investigation is warranted to validate the anti-cancer effects of AIMs in TNF-α, high in an in vivo system." (PMID 33233701, 2020). "Another recent report shows that cancer cell stimulation with the NO donor glyceryl trinitrate (GTN) promotes TNF-mediated cell death in colon and mammary cancer cells." (PMID 32290499, 2020). "We further demonstrated that HPV16 E6 played a key role in TNFα-induced cancer stemness via suppression of the stemness-inhibiting microRNAs miR-203 and miR-200c." (PMID 31911577, 2020). "The expression of VCAM-1 is associated with the activation of inflammatory cytokines, such as TNFα and ROS, and is relevant to the progression of several immunological disorders and cancers." (PMID 32719746, 2020). "In a screen of 16 cancer cell lines, takinib in combination with tumor necrosis factor (TNF) was found to induce cell death (>20%) in 6 out of 16 cell lines." (PMID 32523651, 2020). "Constitutive activation of STAT3 or NF-κB up-regulates major pro-inflammatory cytokines, such as TNFα, IL-1, and IL-6, which can promote cancer cell proliferation, angiogenesis, and metastasis." (PMID 33396715, 2020). "The adhesion assay revealed that AIM significantly inhibited TNF-augmented cancer cell adhesion of MCF–7 cells in a dose-dependent manner." (PMID 32455624, 2020). "This includes changes in invasive membrane structures (blebbing, lamellipodia) and genes related to cancer stemness (Notch1, Oct3), inflammation (NK-κB, TNF, IL8), and cell-cell and cell-matrix adhesion (integrin, MAPK, LINC, FAK, etc.)." (PMID 33585411, 2020). "Studies have suggested that TNF-α sign plays a key role in BC cell migration and its level has great potential to be prognostic cancer biomarkers." (PMID 32849897, 2020). "It has been shown that some multidrug resistant cancer cells indicate more sensitivity against cytotoxic effects of TNF-α compared to their parental cells." (PMID 32742605, 2020). "Further, tumor necrosis factor (TNF) is a key cytokine in inflammation that induces the nuclear factor kappa B (NF-κB) pathway in order to promote cancer cell survival via upregulation of STAT3." (PMID 33076397, 2020). "We also performed a wound healing assay to check the inhibitory activity on cancer cell migration with TNF-α treatment to know its stimulation effect on the cancer cell migration of Hep3B cells." (PMID 33233701, 2020). "Armed with this knowledge, the combination of SMs with radiation was explored to overcome TNF-mediated SM resistance in cancer." (PMID 32053868, 2020).
cancer (continued). "A number of recent studies have shown that plant lectins can modulate extrinsic apoptosis signaling in cancer cells by activating cell surface death receptors that include TNF, TRAIL and FasL." (PMID 32097449, 2020). "Major functional components of this network (TNF, MAPK, TRIM21 and APP) were associated with metabolism and cancer." (PMID 32228434, 2020). "Here, we demonstrate the role of TAK1 in mediating TNF signal cascades in various cancer cell lines." (PMID 32523651, 2020). "TRAIL (tumor necrosis factor [TNF]-related apoptosis-inducing ligand) is a promising anti-cancer agent because it is able to induce apoptosis in various types of cancer cells while it spares normal cells." (PMID 33203916, 2020). "CK2 downregulation has been found to play a significant role in inducing apoptotic processes in cancer cells, especially after induction by TNF-α, and to exacerbate the oxidative stress characteristic of preeclamptic placentas." (PMID 32759710, 2020). "Stimulating human monocytic cells and cancer cells with TNFα triggered increased MCP-1, as previously-reported with TNFα-stimulated human vascular endothelial cells." (PMID 33203088, 2020). "We previously showed that TNF-α signaling-related gene expression was changed in fibroblasts cultured with cancer cells with high metastatic potential." (PMID 32555715, 2020). "With regard to the observed protective effect of TNF on cancer, our study reveals two important clinical considerations." (PMID 32805626, 2020). "TNF‐α is a pro‐inflammatory mediator that performs a crucial roles in malignant tumour processes, for example invasion, motility and metastasis." (PMID 33159487, 2020). "Flavonoids have been shown to inhibit TNFα and MMPs, which both are required for cancer metastasis, and they can also inhibit signaling pathways involved in invasion, including MAPK/ERKs and PI3K signaling." (PMID 33680039, 2020). "Along with that, significantly increased levels of TNFα was found in the pre-neoplastic lesions of several cancers." (PMID 33352869, 2020). "The culmination of inflammatory mediators (Stat3, IL-6, TNF-alpha) guides to an immuno-suppression and following progression of cancer." (PMID 32570802, 2020). "Proinflammatory cytokines tumor necrosis factor (TNF)-α and IL-1β regulate ASS1 in cancer cell lines, and TNF-α has been observed to co-localize with ASS1 in epithelial ovarian cancer." (PMID 32266129, 2020). "The clinical use of TNF as a drug in cancer therapy was found to be restricted by its toxicity, reflected in organ injury and hypotension." (PMID 32410851, 2020). "TNF-α and IL-6 are two indicators of cancer cachexia, and the levels of these two cytokines are usually tested in many studies to determine the therapeutic effect." (PMID 32020864, 2020). "Through a complex regulatory network, after its receptor activation, TNF-α has been found to induce apoptosis or necrosis but also an opposite effect inducing cell growth, invasion or propagation of cancer cells." (PMID 32013102, 2020). "The report by Sonkusre showed that SeNPs induced TNF upregulation, which can activate cancer cell necrosis." (PMID 32357938, 2020). "In this study, we screened a set of ∼120 miRNAs for apoptosis-regulating miRNAs and identified miR-381-3p as a suppressor of TNF-induced apoptosis in various cancer cells." (PMID 32411707, 2020). "TNF and IL-10, are multifunctional cytokines produced by the immune system, has a wide range of biological system including a pro- and anti-cancer effect." (PMID 32693841, 2020). "This study, in conjunction with other observations, therefore indicated that TNFα can serve as a sensitizer to conventional chemotherapeutic agents to kill cancer cells by promoting their apoptosis." (PMID 32225068, 2020). "TNF and IFN-γ are major inducers of apoptosis in cancer cells but some cells escape from TNF- and IFN-γ-induced apoptosis." (PMID 32165639, 2020).
cancer (continued). "And the inflammatory cytokines such as interleukin-6, transforming growth factor-beta, tumor necrosis factor-alpha, and platelet-derived growth factors are also an important factors of cancer pathogenesis." (PMID 31980025, 2020). "KEGG enrichment indicated several pathways regulated by brazilin such as TNF signaling pathway, cellular senescence, and pathways in cancer." (PMID 32986377, 2020). "The pathophysiological relevance of TNF-induced NF-κB activation is highlighted by the reports that TNF-α is very frequently increased in patients with advanced cancers which have high chances to metastasize." (PMID 33233701, 2020). "ADAM17 promoted cancer progression mainly by shedding Tumor Necrosis Factor-alpha (TNF-α) to activate the downstream signaling pathways." (PMID 32637415, 2020). "The serum levels of sTNFR1 and its ligand TNF-α are highly regulated in diverse human cancers and are suggested to be an important determinant of growth and cancer progression." (PMID 33029495, 2020). "In parallel, subclone-specific mutated genes are highly enriched in cancer-related pathways, including MYC target, G2M checkpoints, and mitotic spindle, and immune-related pathways, such as interferon response, TNF-a signaling, and inflammatory response." (PMID 31937348, 2020). "Significantly enough, cancer epithelial cells in the bone produce several inflammatory factors, such as IL-6, IL-8, TNF-α, and CCL2, which continue to promote immune evasion and interfere with normal bone forming and resorption processes." (PMID 33076397, 2020). "Nanoparticles have been found to induce the production of cytokines, of potent anti-cancer properties, for example, the tumor necrosis factor α (TNF-α)." (PMID 33187201, 2020). "We describe four patients whose neurological symptoms were precipitated by potent innate immune system challenges: bladder instillation of BCG, tick bite and an "alternative cancer therapy" with bacterial extracts and TNF-α." (PMID 33362700, 2020). "For this purpose, fresh TILs obtained from a number of surgical specimens of a variety of cancers were stimulated with anti-CD3/CD28 mAbs in combination with TNF blocking agents." (PMID 32292509, 2020). "The cytokines and their receptors utilized through TAMs during cancer progression include IL-6, IL-12, IL-10, IL-23, TNF, and TLRs." (PMID 32283687, 2020). "It has been reported that USP4 can deubiquitinate and stabilize TRAF2/TRAF6 to inhibit TNFα-induced cancer cell migration." (PMID 32549341, 2020). "TNF-α produced by the cancer affects macrophage SINGLEC1 expression, which is found in high levels on tumor-associated macrophages." (PMID 32655574, 2020). "In order to clarify the functions of TNF, measuring salivary TNF levels as an indicator of its in vivo expression in healthy and cancerous groups will be necessary to understand the relationship between TNF gene activity and cancer cell growth." (PMID 32019214, 2020). "Tumor necrosis factor (TNF-α) is an important pro-inflammatory cytokine and is associated with inflammatory diseases or its altered function has been noticed in various cancers." (PMID 32660101, 2020). "Taken together, these results suggest that cellular miR-381-3p expression level in human cancer cell is negatively correlated with cell sensitivity to TNF-induced apoptosis." (PMID 32411707, 2020). "It has been described that p42/p44MAPK and PI3K/Akt are critical for TNFα-induced MMP9 expression in cancer." (PMID 32391269, 2020). "Tumor necrosis factor (TNF)-related apoptosis-inducing ligand (TRAIL) has attracted attention as a potential candidate for cancer therapy." (PMID 32784606, 2020). "It is well known that the tumor necrosis factor TNF pathway affects the survival of cancer patients." (PMID 33584795, 2020).